TTLL7 (tubulin tyrosine ligase like 7)
Description:
Polyglutamylase which modifies tubulin, generating polyglutamate side chains of variable lengths on the gamma-carboxyl group of specific glutamate residues within the C-terminal tail of tubulin. Mediates both ATP-dependent initiation and elongation steps of the polyglutamylation reaction. Preferentially modifies the beta-tubulin tail over an alpha-tail. Competes with monoglycylase TTLL3 for modification site on beta-tubulin substrate, thereby creating an anticorrelation between glycylation and glutamylation reactions (By similarity). Required for neurite growth; responsible for the strong increase in tubulin polyglutamylation during postnatal neuronal maturation (By similarity).
Synonyms: FLJ23033
Tractability: Small molecule: a structure with a bound ligand is known. PROTAC: ubiquitination databases record sites on it.
Gene: Protein-coding gene on chromosome 1 (83,865,024 to 83,999,164, reverse strand). Ensembl gene ENSG00000137941.
Subcellular location: Cell projection, cilium; Cytoplasm, cytoskeleton, cilium basal body; Cell projection, dendrite; Perikaryon
Pathways (Reactome):
Metabolism of proteins: Carboxyterminal post-translational modifications of tubulin
Gene Ontology:
Molecular function: alpha-tubulin binding; beta-tubulin binding; protein-glutamic acid ligase activity, elongating; protein-glutamic acid ligase activity, initiating; tubulin-glutamic acid ligase activity; tubulin binding
Biological process: protein polyglutamylation; microtubule cytoskeleton organization
Cellular component: ciliary basal body; cytosol; perikaryon; cilium; dendrite
Genetic constraint (gnomAD): Loss-of-function variants: 47 observed, 106.21 expected, observed/expected ratio (o/e) 0.44, 90% interval 0.35 to 0.56. The upper end of that interval is the gene's LOEUF score, 0.56, which puts it in group 2 of 6, group 1 being the genes least tolerant of losing a copy. Missense variants: 736 observed, 998.31 expected, observed/expected ratio (o/e) 0.74, 90% interval 0.69 to 0.78. Synonymous variants: 329 observed, 338.46 expected, observed/expected ratio (o/e) 0.97, 90% interval 0.89 to 1.07.
Homologues: Orthologues: chimpanzee TTLL7 (99% identical), macaque TTLL7 (99% identical), dog TTLL7 (95% identical), pig TTLL7 (95% identical), rabbit TTLL7 (95% identical), guinea pig TTLL7 (93% identical), mouse Ttll7 (88% identical), rat Ttll7 (85% identical), tropical clawed frog ttll7 (71% identical), zebrafish ttll7 (68% identical). Paralogues in human: TTLL6 (28% identical), TTLL13 (24% identical), TTLL11 (18% identical), TTLL4 (17% identical), TTLL2 (15% identical), TTLL3 (12% identical), TTLL9 (12% identical), TTLL10 (12% identical), TTLL1 (11% identical), TTLL8 (11% identical), TTLL12 (10% identical), KPRP (7% identical).
Diseases named in the same sentence as TTLL7 in open-access papers:
TTLL7 is named in the same sentence as 10 diseases in open-access papers, as found by Europe PMC text mining. Sharing a sentence is not in itself a finding about the gene and the disease. The quoted sentences say what the papers report.
Alzheimer disease (1 paper, 2011). A progressive, neurodegenerative disease characterized by loss of function and death of nerve cells in several areas of the brain leading to loss of cognitive function such as memory and language. "TTLL7 is a highly specific enzyme that performs β-tubulin polyglutamylation and has been suggested as a candidate gene associated with Alzheimer's disease." (PMID 21311593, 2011).
epilepsy (1 paper, 2023). A brain disorder characterized by episodes of abnormally increased neuronal discharge resulting in transient episodes of sensory or motor neurological dysfunction, or psychic dysfunction. "The result suggests that loss of Ttll1 and Ttll7 genes was associated with the antiseizure function or prevention of epilepsy." (PMID 37238654, 2023). "In 135 min of observation, Ttll1(Het)/Ttll7(Homo) mice had a significantly longer duration of obvious epilepsy-like symptoms (highest score) than WT mice (WT 3.23 ± 0.15, 7KO 3.75 ± 0.10, t = 5.17, p = 0.0066, unpaired t test)." (PMID 37238654, 2023).
Obesity (1 paper, 2011). Accumulation of substantial excess body fat. "Our combined association studies in human and pig in the predefined fatness related pig QTL region revealed three most likely genes, FAM73A, NEGR1 and TTLL7, as being responsible for genetic predisposition to common forms of obesity, especially subcutaneous fat thickness." (PMID 21311593, 2011).
neurological diseases (1 paper, 2023). "Ttll1 and Ttll7 can be potential therapeutic target genes for neurological diseases through the investigation of drugs modulating tubulin polyglutamylation levels." (PMID 37238654, 2023).
TTLL7 also shares sentences with these, for which no sentence is quoted: Blindness (1 paper); breast carcinoma (1); cone/cone-rod dystrophies (1); muscle atrophy (1); retinitis pigmentosa (1); tumor (1).